WDR47 (WD repeat domain 47)
Synonyms: KIAA0893
Tractability: PROTAC: ubiquitination databases record sites on it; its protein half-life has been measured.
Gene: Protein-coding gene on chromosome 1 (108,970,211 to 109,042,169, reverse strand). Ensembl gene ENSG00000085433.
Subcellular location: Cytoplasm, cytoskeleton
Subcellular location (Human Protein Atlas): Actin filaments; Primary cilium
Gene Ontology:
Molecular function: protein binding; protein-containing complex binding
Cellular component: cytoplasm; microtubule; axon; cell body; cytoskeleton; dendrite; growth cone; neuron projection
Genetic constraint (gnomAD): Loss-of-function variants: 32 observed, 97.59 expected, observed/expected ratio (o/e) 0.33, 90% interval 0.25 to 0.44. The upper end of that interval is the gene's LOEUF score, 0.44, which puts it in group 1 of 6, group 1 being the genes least tolerant of losing a copy. Missense variants: 777 observed, 1,144.3 expected, observed/expected ratio (o/e) 0.68, 90% interval 0.64 to 0.72. Synonymous variants: 374 observed, 392.23 expected, observed/expected ratio (o/e) 0.95, 90% interval 0.88 to 1.04.
Homologues: Orthologues: chimpanzee WDR47 (99% identical), macaque WDR47 (99% identical), rabbit WDR47 (98% identical), pig WDR47 (97% identical), dog WDR47 (97% identical), guinea pig WDR47 (96% identical), mouse Wdr47 (96% identical), rat Wdr47 (96% identical), tropical clawed frog wdr47 (82% identical), zebrafish wdr47a (77% identical), zebrafish wdr47b (69% identical), Caenorhabditis elegans nmtn-1 (37% identical), and 1 more.
Diseases named in the same sentence as WDR47 in open-access papers:
WDR47 is named in the same sentence as 27 diseases in open-access papers, as found by Europe PMC text mining. Sharing a sentence is not in itself a finding about the gene and the disease. The quoted sentences say what the papers report.
microcephaly (3 papers, 2022 to 2025). A congenital or acquired developmental disorder in which the circumference of the head is smaller than normal for the person's age and sex. "We report five unrelated families carrying bi-allelic variants in WDR47 presenting with CCD together with other neuroanatomical phenotypes such as microcephaly and enlarged ventricles." (PMID 39609633, 2025). "We suggest that WDR47 variants should be considered in unexplained cases of corpus callosum abnormalities, microcephaly, intellectual disability, and epilepsy." (PMID 39609633, 2025). "We previously showed that Wdr47 deficiency in constitutive knock-out models leads to reduced number of progenitors and increased neuronal death, both of which likely contributing to the microcephaly phenotype." (PMID 39609633, 2025). "Yet, a fraction (nearly 6%) of mice expressing 30% of Wdr47 (Wdr47tm1a/tm1a) survive and display severe neuroanatomical abnormalities including primary microcephaly and severe loss of commissural fibers, including CC, that manifest as hyperactivity and sensory motor gating abnormalities." (PMID 39609633, 2025). "In line with previously characterized Wdr47-deficient mouse models, corpus callosum dysgenesis (CCD) and microcephaly are fully penetrant features observed in all human patients (7/7) (Dataset EV1)." (PMID 39609633, 2025). "Overall, we identified five missense substitutions in the WDR47 gene, that differently impact on WDR47 protein abundance, in seven patients presenting with severe neurodevelopmental delay associated with corpus callosum dysgenesis (CCD), microcephaly and other NAPs." (PMID 39609633, 2025). "This study provides the first evidence of a causal relationship between bi-allelic variants in the WDR47 gene and a complex neurodevelopmental syndrome characterized by corpus callosum dysgenesis (CCD), microcephaly and other neuroanatomical phenotypes in both humans and mice." (PMID 39609633, 2025). "In summary, our data identify WDR47 as an important gene for neuroanatomical disorders, including corpus callosum dysgenesis (CCD) and microcephaly, in both humans and mice." (PMID 39609633, 2025). "Interestingly, the clinical manifestations of the patients are recapitulated in previously studied constitutive Wdr47 KO mouse models that display severe neuroanatomical phenotypes including CCD and microcephaly among other NAPs (Dataset EV1)." (PMID 39609633, 2025).
Lissencephaly (2 papers, 2019 to 2022). A spectrum of malformations of cortical development caused by insufficient neuronal migration that subsumes the terms agyria, pachygyria and subcortical band heterotopia. "There are no direct evidences for ASDs development and WDR37—however, recently, it has been demonstrated that WDR47 shares functional characteristics with PAFAH1B1, which causes lissencephaly." (PMID 31323926, 2019). "WDR47 (WD repeat-containing protein 47, MIM 615734), sharing structural homology with lissencephaly gene LIS1 (PAFAH1B1), participates in core microtubule-mediated processes, including neural stem cell proliferation, radial migration, and growth cone dynamics." (PMID 36277487, 2022).
Alzheimer disease (1 paper, 2025). A progressive, neurodegenerative disease characterized by loss of function and death of nerve cells in several areas of the brain leading to loss of cognitive function such as memory and language. "The only exception is a genome-wide association study (GWAS) that identified WDR47 as a hub gene in Alzheimer’s disease." (PMID 39609633, 2025).
epilepsy (1 paper, 2025). A brain disorder characterized by episodes of abnormally increased neuronal discharge resulting in transient episodes of sensory or motor neurological dysfunction, or psychic dysfunction. "Interestingly, as WDR47 is enriched in both excitatory and inhibitory neurons, it is not surprising that all the patients present with epilepsy (Dataset EV1)." (PMID 39609633, 2025).
frontotemporal dementia (1 paper, 2025). Frontotemporal dementia (FTD) comprises a group of neurodegenerative disorders, characterized by progressive changes in behavior, executive dysfunction and language impairment, as a result of degeneration of the medial prefrontal and frontoinsular cortices. "Interestingly, WDR47 shares similarities with Huntingtin (Htt) and Tau, the proteins whose dysfunctions cause HD and AD/frontotemporal dementia (FTD), respectively." (PMID 39609633, 2025).
heterotopia (1 paper, 2025). "On the same line, given the loss of WDR47 protein in M01 and M02 patients, one can speculate that M01 and M02 newborns presented with heterotopia, that could not be detected by brain MRI." (PMID 39609633, 2025).
lung carcinoma (1 paper, 2023). "From the list of genes that were targeted by the 73 diagnostic miRNAs, DGKE and WDR47 had significant associations with responses to both systemic therapies and radiotherapy in lung cancer." (PMID 37190222, 2023). "DGKE and WDR47 were found with significant associations with responses to both systemic therapies and radiotherapy in lung cancer." (PMID 37190222, 2023). "WDR47 is targeted by hsa-miR-139-5p, which was found to be under-expressed in lung cancer tumors in this study." (PMID 37190222, 2023).
neuroblastoma (1 paper, 2025). Neuroblastoma (NB) is the most common solid, extracranial childhood tumor. "To interrogate the molecular effect of the WDR47 variants, we first assessed WDR47 protein expression levels after overexpression of HA-tagged WT and mutant constructs in N2A neuroblastoma cell line." (PMID 39609633, 2025).
neuronal migration disorder (1 paper, 2025). "One patient (M03) presented with periventricular heterotopia (PVHT), a neuronal migration disorder reflecting Wdr47’s regulatory role in migration." (PMID 39609633, 2025).
oral cavity tumors (1 paper, 2022). "Interestingly, three patients with oral cavity tumors (51.1, 207, and 339) presented gains encompassing WDR genes (WDR83, WDR19, and WDR47, respectively)." (PMID 36552033, 2022).
Parkinson’s (1 paper, 2025). "We identified disruptions in a significant number of Alzheimer’s and Parkinson’s-related genes in Wdr47-deficient primary neuronal cultures, corroborating a recent study that recognized WDR47 as a hub gene in Alzheimer’s." (PMID 39609633, 2025).
primary ciliary dyskinesia (1 paper, 2021). A rare, genetically heterogeneous, primarily respiratory disorder characterized by chronic upper and lower respiratory tract disease. "Wdr47 deficiency in mouse multicilia results in complete loss of CP, rotatory beat, and primary ciliary dyskinesia." (PMID 34608154, 2021).
neurological disorder (2 papers, 2022 to 2025). "The neuroanatomical defects found in Wdr47 KO result in hyperactivity and sensory motor gating abnormalities both in male and female mice, suggesting a link between WDR47 and neurological disorder." (PMID 36277487, 2022). "Despite the clear role of Wdr47 in mouse brain development and function, there is yet no clear association of WDR47 variants with neurological disorders in humans." (PMID 39609633, 2025).
infection (1 paper, 2021). The state of being infected such as from the introduction of a foreign agent such as serum, vaccine, antigenic substance or organism. "To understand whether excessive Camsaps could also functionally compensate for the Wdr47 deficiency in mEPCs, we overexpressed GFP-tagged Camsaps or Centrin1 (negative control) in Wdr47−/− mEPCs through lentiviral infection." (PMID 34608154, 2021).
neurodegenerative disease (1 paper, 2025). A disorder of the central nervous system characterized by gradual and progressive loss of neural tissue and neurologic function. "The molecular alterations we observed in Wdr47-deficient developing neurons resemble pathological mechanisms that underlie neuronal loss in neurodegenerative diseases." (PMID 39609633, 2025).
WDR47 also shares sentences with these, for which no sentence is quoted: Intellectual disability (2 papers); autism spectrum disorder (1); brain disorder (1); cervical cancer (1); corpus callosum dysgenesis (1); Hydrocephalus (1); Neurodevelopmental delay (1); Periventricular heterotopia (1); periventricular nodular heterotopia (1); sinusitis (1); Situs inversus totalis (1); ventricular septal defect (1).